ASB1 (ankyrin repeat and SOCS box containing 1)
Description:
Probable substrate-recognition component of a SCF-like ECS (Elongin-Cullin-SOCS-box protein) E3 ligase complex which mediates the ubiquitination and subsequent proteasomal degradation of target proteins. Mediates Notch-induced ubiquitination and degradation of TCF3/E2A and JAK2. Functions as a tumor suppressor by enhancing CHCHD3 'Lys-48'-linked ubiquitination, leading to inhibition of the CHCHD3/ROS signaling pathway. Suppresses TAB2-linked 'Lys-48' polyubiquitination and consequently facilitates the initiation of NF-kappa-B and MAPK signaling cascades. May play a role in testis development (By similarity).
Synonyms: ASB-1
Tractability: PROTAC: ubiquitination databases record sites on it.
Gene: Protein-coding gene on chromosome 2 (238,426,742 to 238,452,250, forward strand). Ensembl gene ENSG00000065802.
Subcellular location: Cytoplasm
Subcellular location (Human Protein Atlas): Nucleoplasm
Pathways (Reactome):
Immune System: Antigen processing: Ubiquitination & Proteasome degradation
Metabolism of proteins: Neddylation
Gene Ontology:
Molecular function: protein binding; ubiquitin protein ligase activity; ubiquitin-like ligase-substrate adaptor activity
Biological process: protein ubiquitination; negative regulation of cytokine production; proteasome-mediated ubiquitin-dependent protein catabolic process; intracellular signal transduction
Cellular component: cytoplasm; ubiquitin ligase complex; cytosol
Genetic constraint (gnomAD): Loss-of-function variants: 18 observed, 28.08 expected, observed/expected ratio (o/e) 0.64, 90% interval 0.44 to 0.95. The upper end of that interval is the gene's LOEUF score, 0.95, which puts it in group 4 of 6, group 1 being the genes least tolerant of losing a copy. Missense variants: 397 observed, 464.25 expected, observed/expected ratio (o/e) 0.86, 90% interval 0.79 to 0.93. Synonymous variants: 189 observed, 194.26 expected, observed/expected ratio (o/e) 0.97, 90% interval 0.86 to 1.1.
Homologues: Orthologues: chimpanzee ASB1 (98% identical), macaque ASB1 (95% identical), mouse Asb1 (94% identical), pig ASB1 (93% identical), dog ASB1 (92% identical), rat Asb1 (91% identical), rabbit ASB1 (90% identical), guinea pig ASB1 (90% identical), tropical clawed frog asb1 (59% identical), zebrafish asb1 (58% identical), Caenorhabditis elegans ZK792.4 (23% identical). Paralogues in human: ANKRD16 (26% identical).
Diseases named in the same sentence as ASB1 in open-access papers:
ASB1 is named in the same sentence as 8 diseases in open-access papers, as found by Europe PMC text mining. Sharing a sentence is not in itself a finding about the gene and the disease. The quoted sentences say what the papers report.
ischemic cardiomyopathy (1 paper, 2018). Ischemic cardiomyopathy is a cardiomyopathy in which a weakness in the muscle of the heart due to inadequate oxygen delivery to the myocardium with coronary artery disease being the most common cause. "A recent study of ischemic cardiomyopathy in a Spanish population detected significant differential DNA methylation patterns for another member of the ASB family (ASB1 gene), and further highlighted the potential role of DNA methylation of ASB family members for stroke and cardiovascular phenotypes." (PMID 30237808, 2018).
prostate carcinoma (1 paper, 2025). A carcinoma that arises from epithelial cells of the prostate gland. "This investigation further elucidated that ASB1 interacts with CHCHD3 and enhances its K48-linked ubiquitination, thereby influencing the behavior of prostate cancer cells." (PMID 40771930, 2025). "Their analysis showed that ASB1 expression was significantly downregulated in prostate cancer tissues compared to paraneoplastic tissues, which was further confirmed by qRT-PCR experiments, and that silencing of ASB1 promotes prostate cancer cell proliferation in vitro." (PMID 40771930, 2025).
staphylococcus aureus infection (1 paper, 2021). An infectious process in which the bacteria Staphylococcus aureus is present. "According to the ROC curve, ASB1, UBB, and MKRN1 can effectively act as potential diagnostic markers for distinguishing samples of Staphylococcus aureus infection from healthy counterparts." (PMID 34852788, 2021).
infection (2 papers, 2013 to 2021). The state of being infected such as from the introduction of a foreign agent such as serum, vaccine, antigenic substance or organism. "Therefore, we speculated that inhibition and down-regulation of ASB1 in the late stage of infection can against the inflammatory injury induced by Staphylococcus aureus." (PMID 34852788, 2021).
ASB1 also shares sentences with these, for which no sentence is quoted: idiopathic pulmonary fibrosis (1 paper); osteonecrosis (1); osteoporosis (1); Stroke (1).